TLR2 (toll like receptor 2)
Diseases named in the same sentence as TLR2 in open-access papers (continued):
Sharing a sentence is not in itself a finding about the gene and the disease.
viral infection (continued). "IM can produce type I IFNs during some viral infections through TLR2 signaling." (PMID 33806810, 2021). "Moreover, TLR2 activation by bacterial products produced by the gut microbiota, is necessary for the recruitment of mast cells to sites of viral infection and the further release of cathelicidin, a mast cell-derived antiviral protein." (PMID 33243230, 2020). "In addition, during vaccinia virus infections, the activation of TLR2 by bacterial products is essential for recruiting mast cells to sites of viral infection." (PMID 33243230, 2020). "Virus infection and complex ligands could provide broader and more sustained signaling to facilitate TLR2 involvement in NK cell activation." (PMID 32696994, 2020). "Furthermore, TLR2 signal can up-regulate the tight junction proteins in epithelial cells which can enhance the tolerance to viral infection." (PMID 30930867, 2019). "Thus, targeting CLEC5A/TLR2 have the potential to underpin novel strategies for treating acute viral infections." (PMID 31867016, 2019). "Since previous reports suggest TLR2 or 4 is in charge of viral infection we presumed that spore might trigger MyD88 signaling upon direct engagement with TLRs on AM." (PMID 30930867, 2019). "Reporter assays have also linked missense SNPs that are located within TLR2 and TLR5 to a differential reactivity to Salmonella enterica and within TLR3 to different responses to stimulation by poly(A:C), a synthetic acid that emulates viral infection." (PMID 27036198, 2016). "Together indicating that TLR2 may play an important role in viral infection, particularly HIV, and needs to be investigated further." (PMID 26347747, 2015). "On the other hand, microglia from TLR2−/− mice display delayed and attenuated production of reactive oxygen species (ROS) following viral infection and suffer lesser neuronal oxidative damage in mixed neural cell cultures, as compared to HSV-infected cells from wild-type animals." (PMID 25918478, 2015). "We presume that higher level of TLR2 after 8 hours of virus infection might have contributed to the observed immunosuppression at 24 hours following virus infection in our study." (PMID 25105760, 2014). "Considering the specialized role of NK cells in the control of viral infections, it is tempting to speculate that intracellular TLR2 could serve as a mechanism to ensure its activation in response to intracellular pathogens." (PMID 23440148, 2013). "In the context of virus infections, TLR4 and TLR2 may also recognizes damage-associated molecular patterns (DAMPs) released during infection." (PMID 23435233, 2013). "In addition, Staphylococcus adherence to epithelial cells is enhanced following viral infection which causes increased expression of host cell receptors such as ICAM-1 and downregulation of TLR2." (PMID 22567325, 2011). "The observation that activation of the pattern recognition receptor TLR2 quickly recruits NK cells to an inflammatory site underscores the importance of both TLR2 and NK cells as critical components of innate immunity during bacterial, fungal and viral infections." (PMID 32696994, 2020). "Meanwhile, the monocyte surface molecule CD14 cooperates with TLR2 in response to viral infection, activating nuclear factor-κB (NF-κB)–dependent transcription of genes encoding inflammatory cytokines, which may be inhibited via blockade of TLR2-mediated signaling." (PMID 32848776, 2020). "Thus, such a cross-regulation among PRRs (TLR2 and TLR3) causing subsequent downregulation of TLR3 and TICAM1 may result in weakened innate immunity against viral infections." (PMID 29449840, 2018). "However, virally induced TLR2-dependent cellular activation has been shown to contribute to viral spread and pathogenesis due to enhanced expression of various viral entry receptors, thereby increasing the viral infection." (PMID 27531999, 2016).
viral infection (continued). "Such priming might work systemically during virus infection as free viral proteins capable of acting as TLR2 ligands are shed into the circulation from an infected tissue and travel to uninfected sites and encounter TLR2-expressing innate immune cells." (PMID 23853595, 2013). "Additionally, having identified the differences in TLR2-dependent cytokine responses between pathogenic and non-pathogenic virus infection, this work provides an avenue for development of therapeutics." (PMID 23202459, 2012). "Since IL-12 and IL-1 have been implicated in regulating NK cell activation and function in other models of viral infection, we investigated whether the TLR2-dependent NK cell response to VV infection was due to TLR2-induced secretion of pro-inflammatory cytokines." (PMID 20300608, 2010). "Compared to other feline viruses, such as FHV-1, TLR2 and TLR4 were also up-regulated at early stages (3 hpi vs. 6 hpi) of virus infection." (PMID 40872699, 2025). "While this study has mainly focused on the immunomodulatory role of TLR2 agonist in the prophylactic model of B. anthracis infection, a broader understanding of how TLR ligands modify bacterial and even viral infections is critical." (PMID 35369443, 2022). "TLR2 and TLR4 have also been studied to recognize the viral structural proteins, which results in the production of inflammatory cytokines against the viral infection." (PMID 36679906, 2022). "The viral infection led to significant overexpression of PRR genes, mainly DDX58, IFIH1, TLR2, and TLR4." (PMID 34937196, 2021). "Toll-like receptor 2 (TLR2) is a major pattern recognition receptor (PRR) and mediates viral infection via the TLR2/MyD88 pathway." (PMID 34768911, 2021). "As key components of intercellular signal transmission and regulation, the expression of cytokines including inflammatory factors (IL-1β and IL-8) and toll-like receptors (TLR2, TLR3, and TLR7) increased significantly after viral infection." (PMID 33897703, 2021). "In this study, we focused on TLR1, TLR2, TLR4, TLR5, TLR6 and TLR9 expression fold changes in two genital epithelial cells (HEC-1-A and VK2) after viral infection." (PMID 30419930, 2018). "Taken together, these publications highlight the role of TLR2 and its heterodimers as important extracellular PRRs for viral PAMP recognition, resulting in increased cellular activation and facilitating viral infection in permissive cells." (PMID 27531999, 2016). "Both TLR2 and TLR4 have been associated with recognition of DAMPs released from necrotic infections, including heat shock proteins (HSPs), high mobility group box-1 (HMGB1) protein, and oxidized phospholipids, all of which may be released during virus infections." (PMID 23435233, 2013). "In addition, it has been reported that the participation of TLR6, TLR2, and TLR7 actively participates against some viral infections, such as the SARS-CoV-2 virus, which is recognized by TLR2 and subsequently by TLR7 for an effective antiviral response." (PMID 40573281, 2025). "Given that innate antiviral immunity is the first line of defense against viral infections, we hypothesized that EV71 activates innate immunity via TLR2 heterodimer recognition." (PMID 37207203, 2023). "Current studies have demonstrated that the SARS-CoV-2 envelope (E) protein is a pro-inflammatory factor sensed by Toll-like receptor 2 (TLR2), suggesting the pathological feature of E protein is independent of viral infection." (PMID 37158916, 2023). "Investigation of the mechanisms and consequences of TLR2 signaling have primarily focused on pathogen-specific induction of type I IFNs and TNF, largely in response to S. aureus exposure or viral infection." (PMID 34755600, 2021). "Expression of those receptors sensitizes endothelial cells to the action of several Gram-negative (Tlr4) and positive (Tlr2) bacteria along with several viral infections (Tlr3)." (PMID 32038494, 2019).
viral infection (continued). "Potential explanations for this are the association of NET formation with lung injury, and the central role of inflammasome activation in viral pathology; blockade of CLEC5A/TLR2 attenuates NET formation and inflammasome activation and is thus beneficial to the host during acute viral infection." (PMID 31867016, 2019). "Another study indicated that Mtb is able to induce the production of TNF-α and IL-1β in RAW264.7 cells and that it activates the NF-κB pathway through TLR2-mediated signaling, thereby contributing to the induction of IRF-1, one of the most potent ISGs against viral infection." (PMID 30717477, 2019). "Indeed, viral proteins, similar to viral nucleic acids or replication intermediates, can in some cases also function as PAMPs, specifically recognized by certain host PRRs, such as TLR2 and TLR4, to modulate the IFN responses during viral infection." (PMID 28848548, 2017). "It is documented that TLR2 and TLR4 recognize viral capsid proteins and envelope glycoproteins in measles virus, hepatitis C virus, murine leukemia virus, mouse mammary tumor virus and coxsackievirus B4 virus infections." (PMID 23671700, 2013). "Furthermore, the two previous studies documented that TLR2 activation of type I IFN responses to TLR ligands occurs within intracellular compartments, and that TLR2 signals from the phagosome in response to viral infection or synthetic TLR2 ligands." (PMID 22432012, 2012). "The present work, together with findings from previous studies of our group, indicates that Dectin-1, TLR2, and TLR4 are important PRRs for the activity of MDSCs in pulmonary PCM, as already demonstrated in cancer and other diseases, such as other fungal, bacterial, and viral infections." (PMID 39035356, 2024). "Also, Candida cell wall components may bind to toll-like receptors (TLRs), primarily TLR-2 and TLR-4, inducing the production of tumor necrosis factor (TNF)-α and type I IFNs that eliminate viral infections." (PMID 37573268, 2023). "TLR2 and TLR4 have both been found during infection by HCV and HCV/HIV-1 co-infection, indicating that the inhibitory effect of quercetin towards TLR2 and TLR4 could also apply during viral infections, lowering the inflammatory response of the patient." (PMID 37513186, 2023). "Previously, cytoskeletal F-actin is identified as a ligand for C-type lectin member 9A (CLEC9A), and chaperone HSP70 is shown as a ligand for TLR2 and TLR4; therefore, these upregulated components may be responsible for DV-EVs-induced inflammatory reactions during viral infection." (PMID 34116654, 2021). "Stimulation of MDMs with the TLR1/TLR2 agonist (mimicking bacterial infection) resulted in a strong increase of CD127 expression, comparable to that after LPS exposure, whereas no relevant induction of CD127 was observed after stimulation with the TLR3 agonist (mimicking viral infection)." (PMID 33584648, 2020). "Indeed, in the central nervous system TLR2 is essential for expression of inflammatory cytokines (i.e., TNF-α and IL-6) and chemokines by monocytes (i.e., CCL2), lymphocytes (i.e., CCL22 and CCL27) and neutrophils (i.e., RANTES) during viral infection." (PMID 30254622, 2018). "Future research will have to delineate whether some of the reported virus-induced immune responses mediated via TLR2 and TLR4 are due to recognition of DAMPs rather than direct recognition of the viruses, and thus further characterize the role of TLR2 and TLR4 during virus infection in humans." (PMID 23435233, 2013). "Because DV-EVs can activate CLEC5A and TLR2 to induce NET formation and proinflammatory cytokine release, simultaneous blockade of CLEC5A and TLR2 by a bi-specific mAb may be able to protect host from DV-EVs-induced NETosis and inflammatory reactions during viral infections." (PMID 34116654, 2021).
viral infection (continued). "While some studies have investigated TLR2- and TLR4-mediated responses to viral infections using murine B cell models, similar studies have not been performed in human B cells as they express little or no TLR2/4." (PMID 34293057, 2021). "The use of mice lacking TLR2-signaling needed to control responses to IAV that showed increased bacterial shedding and a looser bottleneck confirmed these effects of viral infection." (PMID 27732665, 2016). "Interestingly, infection with both viruses markedly promoted the expression of TLR1 and TLR2, which are sensors of bacterial components, which may be explained by the up-regulation of IFNα and IFNγ that could enhance the expression of TLR1, TLR2, TLR3, and TLR7 in viral infections." (PMID 27916934, 2016). "In addition, the red gene signature includes TLR2, TLR4, and TLR8, which are not prominent pDC receptors but may play a role in pDC activation under specific conditions, such as during viral infection or in inflamed tissues." (PMID 31552042, 2019).
COVID-19 (102 papers, 2020 to 2026). A disease caused by infection with severe acute respiratory syndrome coronavirus 2. "In this context, the following TLRs have been associated with the severity of COVID-19: TLR2, TLR3, TLR4, TLR7, TLR8 and TLR9." (PMID 41011507, 2025). "FURIN, IFNL4, and TLR2 gene variants are associated with the risk of COVID-19 occurrence as well as increased severity and poor outcomes in Egyptian patients." (PMID 38703289, 2024). "We investigated the association of three substantial gene polymorphisms (FURIN, IFNL4, and TLR2) with COVID-19 disease susceptibility and severity to help predict prognosis." (PMID 38703289, 2024). "The remaining IL6R, IFNG, TLR4, and TLR2 genes (feature gene) were the most likely COVID-19 pathogenic genes that progressed into CRS." (PMID 38165854, 2024). "Thereby, the present study aimed to investigate the association of three substantial gene polymorphisms (FURIN, IFN4, and TLR2) with COVID-19 susceptibility and severity in Egyptian patients." (PMID 38703289, 2024). "They showed a significantly increased risk of severe COVID-19 in carriers of TLR2 rs57443708 and/or TLR4 rs4986791 variants." (PMID 38433829, 2024). "The TLR-2 expression intensity showed that COVID-19 patients with the C allele showed high TLR-2 expression compared with patients’ carriers of TT genotypes (rs3804099 and rs3804100) in naïve active B cells (p = 0.0485)." (PMID 39456843, 2024). "The FURIN, IFNL4, and TLR2 genotypes and their alleles differed significantly between COVID-19 patients and controls, as well as between patients with severe or critical illness and those with a non-severe presentation." (PMID 38703289, 2024). "Toll-like receptors (TLRs) have been associated with the pathogenesis of COVID-19 in particular TLR2 and 4 that are expressed by macrophages." (PMID 39147987, 2024). "In conclusion, FURIN, IFNL4, and TLR2 gene variants are associated with the risk of COVID-19 occurrence and linked to increased severity and worse outcomes in Egyptian patients." (PMID 38703289, 2024). "According to a multivariable regression analysis, FURIN (C/T + T/T) and TLR2 (T/C + C/C) mutants were associated with COVID-19 susceptibility, with odds ratios of 3.293 and 2.839, respectively." (PMID 38703289, 2024). "This work looked for associations between risk factors and the TLR2 SNP rs3804100 in Health Institution workers and COVID-19." (PMID 37895256, 2023). "So, this present study is a pioneer in the search for associations between this TLR2 SNP and the severity and manifestations of COVID-19 in the Brazilian population and the second to investigate these associations with the disease worldwide." (PMID 37895256, 2023). "As for the involvement of TLRs in COVID-19, a single cell-based computational method with the dataset of bronchoalveolar lavage from patients with mild and severe COVID-19 identified TLR2 as a pathogenic factor for the hyperinflammatory response." (PMID 36703213, 2023). "This study demonstrates that SARS-CoV-2-activated platelets produce EVs to enhance thromboinflammation via CLEC5A and TLR2, and highlight the importance of CLEC5A and TLR2 as therapeutic targets to reduce the risk of ARDS in COVID-19 patients." (PMID 35820906, 2022). "TLR2 senses the SARS-CoV-2 envelope (E) protein, and expression of TLR2 and its adaptor MyD88 are associated with COVID-19 disease severity." (PMID 36419185, 2022). "For these reasons, further detailed studies are required to understand the pathogenic interaction between SARS-CoV-2 and TLR2 and the potential of TLR2 as target for COVID-19 treatment." (PMID 35396576, 2022). "Since death and severe cases of COVID-19 are associated with a hyper-inflammatory response, TLR2 antagonists can be tested for their capacity to alleviate the hyper-inflammatory response in SARS-CoV-2 infection or S protein stimulation." (PMID 35205112, 2022).